TNF (tumor necrosis factor)
Diseases named in the same sentence as TNF in open-access papers (continued):
Sharing a sentence is not in itself a finding about the gene and the disease.
tumor (continued). "IgE antibodies recruit macrophages through the TNFα/MCP-1 signaling pathway, enhance anti-tumor immune responses." (PMID 41357192, 2025). "IFN-γ and TNF-α contribute to the anti-TME by promoting tumor cell apoptosis, enhancing antigen presentation, and recruiting other immune cells to the tumor site." (PMID 40227601, 2025). "Th1 releases anti‐tumor cytokines, such as IFN‐γ, IL‐2, and TNF‐α, and enhances the ability of antigen presentation of DCs via the CD40/CD40L signaling pathway." (PMID 40257446, 2025). "In HNSCC, radiation induces tumor cell upregulation of chemokine receptor type 2 (CCR2), resulting in the accumulation of TNFα‐producing monocytes and Tregs." (PMID 41346571, 2025). "Reactive oxygen species (ROS), nitric oxide (NO), and a spectrum of pro-inflammatory cytokines such as IL-6, TNF, and IFN-γ can exert mutagenic effects on tumor cells and their surrounding microenvironment." (PMID 40821768, 2025). "Cells isolated from the spleens and tumor tissues were stained for surface markers (CD45, CD3, CD4, and CD8) and intracellular markers (granzyme B, IFN-γ, TNF-α, and FoxP3)." (PMID 40969744, 2025). "For example, butyrate-producing R. intestinalis suppresses tumor growth by expanding cytotoxic granzyme B+, IFN-γ+ and TNF-α+ CD8+ T cells, concurrently enhancing anti-PD-1 efficacy in mice with MSS CRC." (PMID 40770084, 2025). "This M1 dominance enhanced CD8+ T cell infiltration and activation through augmented IL-12/TNF-α secretion, ultimately manifesting as elevated IFN-γ production and intensified tumour cell apoptosis." (PMID 40225866, 2025). "Tumor necrosis factor (TNF), known for its anti-tumor activity in cancer cells, plays a role in inflammation, differentiation, proliferation, and apoptosis as a member of the TNF cytokine superfamily." (PMID 40809844, 2025). "These strategies operate by either inhibiting the TNF-alpha/TNFR1 pathway or disrupting the RIPK1-RIPK3-MLKL signaling cascade, thereby limiting vascular adaptability and preventing tumor recurrence." (PMID 41584509, 2025). "We performed a correlation analysis between the levels of TNF-α and IL-1β expression in macrophages and UPP1 levels in tumor cells." (PMID 41243973, 2025). "This section focuses on the critical signaling pathways and their biological significance of TAMs within the tumor microenvironment, specifically addressing the TGFβ, WNT, PI3K, and TNF pathways." (PMID 41041337, 2025). "TAMs promote tumor progression via key signaling pathways, including TGF-β/BMP, TNF-α/Wnt, IL-6/STAT3/IRF4, and Wnt/β-catenin, each regulating cell motility, survival, and immune suppression." (PMID 41459539, 2025). "They exert potent anti-tumor effects by secreting cytokines such as IFN-γ, IL-4, and TNF-α, engaging in direct cytotoxicity, and recruiting immune effectors like CD8+ T cells, DCs, and NK cells." (PMID 39941775, 2025). "Macroporous hydrogel (M1LMHA) can secrete various factors, including TNF-α, IFN-γ, and IL-12, and it exerts anti-tumor effects on melanoma by repolarizing M2-type to M1-type macrophages through the NF-κB pathway." (PMID 40034694, 2025). "LNT-SeNPs, in combination with TNF-α, significantly inhibited tumor growth in CT26 tumor-bearing mice after 2 weeks of treatment." (PMID 40244191, 2025). "Key inflammatory mediators within the tumor microenvironment include cytokines such as macrophage migration inhibitory factor (MIF), tumor necrosis factor-alpha (TNF-α), and interleukin-6 (IL-6)." (PMID 41011005, 2025). "They secrete pro-inflammatory cytokines and chemokines, including TNF-α, IL-1β, and CCL18, which facilitate tumor cell proliferation, angiogenesis, and metastasis." (PMID 41280929, 2025).
tumor (continued). "Here, we demonstrate that sensitized tumor cells fail to initiate inhibitory RIPK1 phosphorylation at site S25 upon T cell attack, thereby foregoing a pro-survival checkpoint early in TNF signal transduction." (PMID 41315176, 2025). "The tumor microenvironment (TME) is inherently inflammatory, driven by persistent production of pro-inflammatory cytokines (e.g., IL-6, IL-1β, TNF-α), chemokines, ROS, and activation of transcription factors such as NF-κB and STAT3." (PMID 41020838, 2025). "For instance, MMP-7 and MMP-9 have been shown to influence the availability of cytokines like interleukin-6 (IL-6) and tumor necrosis factor-alpha (TNF-α), modulating inflammatory signaling and dampening immune cell responses in the tumor microenvironment." (PMID 40265458, 2025). "Concurrently, immune checkpoint inhibition remodels the tumor microenvironment, enabling cytokines—such as IFN-γ and TNF-α secreted by CD8+ T cells, NK cells, and macrophages—to exert dual regulatory effects on HER2 expression." (PMID 41550934, 2025). "In early metastasis, osteocytes secrete TNFα, mediated by IFT88 of their primary cilia, which suppresses tumor cell proliferation." (PMID 40301543, 2025). "Tumor cell-derived prostaglandin E2 (PGE2) and tumor necrosis factor induce TAMs to secrete IL-1β, which in turn enhances PGE2 production and tumor necrosis factor in cancer cells, perpetuating a pro-inflammatory state." (PMID 40861469, 2025). "In malignant breast biopsies, TNF‐α was abundant and primarily secreted by TAM “hotspots,” targeting tumor and endothelial cells." (PMID 40685820, 2025). "RIPK1, a key regulator of downstream TNF signaling, has been shown to be essential for CD8 T cell-mediated cytotoxicity, as tumor cells can be driven into RIPK1-dependent apoptosis (RDA) under these conditions." (PMID 41315176, 2025). "Adipose tissue serves as a reservoir of proinflammatory adipokines, such as tumor necrosis factor α (TNFα), interleukin (IL) 6, IL‐8, and chemokine (C‐C motif) ligand (CCL) 2, all of which are involved in tumor progression." (PMID 40111100, 2025). "Upregulation of intracellular lipid peroxidation triggers the activation of p38, a stress-reactive protein, and T cell ferroptosis, leading to downregulation of IFN-γ and TNF-α, which results in the dysfunction of CD8+ T cells and tumor immune escape." (PMID 41035634, 2025). "In vivo studies further confirmed that FF suppressed tumor growth, reduced serum levels of ALT, AST, TNF-α, and IL-17B in mice, and modulated the expression of core target genes." (PMID 40630198, 2025). "Accordingly, the combination treatment increased tumor antigen-specific CD8+ T cells, which produce multiple effector cytokines, such as IFN-γ and TNF-α, in the dLNs and the TME." (PMID 39782686, 2025). "This is evidenced by the upregulation of granzyme B, IFN-γ, and TNF-α expression in CD8+ T cells isolated from blood, spleen, and tumor tissues." (PMID 40495147, 2025). "The results showed that there were was activated signaling of TNF, VEGFC and EGFR from TMGs-high epithelial niches to endothelial cells, indicating hyperactivated angiogenesis in tumor stromal tissues and a potential response to VEGF blockage." (PMID 40216815, 2025). "Lastly, Tregs secrete tumor-promoting cytokines such as TGF-β, IL-10, and IL-6, whereas tumor-suppressing CD8+ and NK cells secrete IFN-γ, TNF-α, etc.." (PMID 41369383, 2025). "Loss of NLRP3 disrupted this process, leading to heightened Th17 inflammatory output (IFN-γ, Granzyme B, TNF-α) and restored CD8+ T-cell cytotoxicity, ultimately constraining tumor growth." (PMID 41291696, 2025). "Specifically in this experiment, SB demonstrated the ability to decrease the blood concentration of tumor specific markers such as CEA, TNF-alpha, IL-6 and liver function markers (including ALT and AST) in the treated groups." (PMID 40712409, 2025).
tumor (continued). "The combination of RPLP0 knockdown and anti-PD-1 treatment resulted in significantly suppressed tumor growth and prolonged survival in mice, accompanied by elevated levels of IFN-γ and TNF-α in serum samples, indicating enhanced anti-tumor immunity." (PMID 40777041, 2025). "The macrophagehigh ductal cell type 2 samples showed a higher number of tumor cells expressing the NF-κB target genes TNFAIP3 and CXCL1 compared to macrophagelow samples, consistent with the known role of TNF in activating NF-κB signaling in PDAC." (PMID 40634284, 2025). "The available data show that the immunohistochemical expression of TNF-α was increased in NET groups with higher proliferation rates, as well as in those with higher tumor grades." (PMID 40507492, 2025). "They release immunosuppressive cytokines such as IL-10, IL-4, IL-13, IDO and TGF-β, reducing TNFα and INF-γ levels in effector CD4+ T cells, inhibiting APCs function, and downregulating tumor-specific cytotoxicity within the immune response." (PMID 41208963, 2025). "With tumor progression, CD8+ T cells gradually lose their production of IL-2 and TNF-α, as well as their cytotoxic function." (PMID 40070825, 2025). "As proved by the cancer immunosurveillance theory, spectrum of inflammatory mediators is initially stimulated by T cells recognized specific tumor antigens, exerting pivotal antitumor role of various aspects, such as IFN‐γ and TNF‐α." (PMID 41427020, 2025). "The upregulation of key mediators such as TNF, IL1A/B, INFG, INFA2, and TGFB1 in tumor-educated immune cells suggests a shift toward a pro-inflammatory yet immunosuppressive phenotype." (PMID 41514627, 2025). "In vivo, we demonstrated that VS-secreted factors reach the inner ear, with elevated TNF-α and TWEAK in the perilymph and blood of tumor-bearing mice with impaired hearing." (PMID 39923035, 2025). "Combination therapy also led to significant increases in both the tumor CD8+ IFN-γ+ and IFN-γ+ TNF-α+ T cells." (PMID 40229241, 2025). "Systemic inflammation, driven by proinflammatory cytokines such as tumor necrosis factor-α (TNF-α), interleukin (IL)-6, and IL-1β, produced by both the tumor and the host, is involved in the pathogenesis of cancer cachexia." (PMID 40136406, 2025). "Although we found some mild CD8+ T cell dependence of IL-6, IL-10, VEGF, and IL-1α in the tumor bed of LLCova-bearing mice, the biggest difference was evident in the proinflammatory cytokines IFN-γ and TNF-α." (PMID 40553564, 2025). "This study provides compelling evidence that VS-secreted TNF-α and TWEAK act synergistically to drive tumor-induced SNHL." (PMID 39923035, 2025). "The LUAD_P06T, HCC_P08T, CRC_P09T, GC_P02T, and BC_P02T tumour cell subclusters, on the other hand, were more active in the EGFR, MAPK, NFκB, and TNF-α pathways." (PMID 39877290, 2025). "Histopathological analysis revealed granuloma formation at the tumour site when C. acnes was present, alongside elevated expression of the pro-inflammatory markers IFN-γ and TNF-α, thus harnessing C. acnes ability to trigger a strong immune response." (PMID 41514871, 2025). "Cytokines such as TNF-α, TGF-β, IL-6, and IL-10 are pivotal players in these processes, driving inflammation, tumor progression, and immune suppression." (PMID 40933989, 2025). "JNK can also induce the secretion of TNF-α, play a role in combination with TNF receptor 1, and promote the role of Epithelial-Mesenchymal Transition (EMT) in the tumor environment to promote tumor proliferation." (PMID 39925809, 2025). "In contrast, other bacterial species like Helicobacter pylori can counter tumor progression by reducing M2-type TAM infiltration and downregulating proinflammatory and tumorigenic cytokines, including TNF-α, IL-1, and IL-23." (PMID 40255905, 2025). "Similar to before, LY96 positive macrophages secrete TNF and TGFB1 that act on tumor cells, thereby enhancing tumor cell proliferation." (PMID 40620715, 2025).
tumor (continued). "The deficiency of STAB1 induced the elevation of inflammatory cytokines (IL1β, IL2, IL12p70, TNFα) and chemokines (CCL3, CCL4, CCL5) in tumor-bearing mice." (PMID 41007347, 2025). "Circulating cytokines, including IL-6, IL-8, and tumor necrosis factor-alpha (TNF-α), correlate with systemic inflammation, tumor burden, and immunotherapy resistance." (PMID 40881677, 2025). "GLIS was also reported to stimulate the production of TNF-α, IL-1, and nitric oxide (NO) in the TME of tumor-bearing mice." (PMID 40733125, 2025). "These M2 macrophages support tumor growth through immunosuppressive actions, angiogenesis, and extracellular matrix remodeling, while also secreting factors like IL-6 and TNF-α that reinforce CSC stemness and contribute to tumor progression and metastasis." (PMID 40330466, 2025). "In a xenograft model, combination treatment with anti-PD-L1 and anti-CD73 antibodies significantly suppressed tumor growth, increased the number of tumor-infiltrating CD8+ T cells, and enhanced IFN-γ and TNF-α production by these T cells." (PMID 40002883, 2025). "Although cytokines such as IL-2 and TNF-α are also indicative of immune activation, IFN-γ was selected as the primary marker due to its direct relevance to anti-tumor activity." (PMID 40643554, 2025). "NCR+ ILC3s tend to be anti-tumoral, producing IL-22 and TNF in contexts such as early-stage lung cancer and mucosal immunity, whereas NCR- ILC3s typically produce IL-17 and support tumor growth in CRC, liver, and pancreatic cancers." (PMID 40963622, 2025). "TNF-α is a crucial inflammatory mediator within the TME, originating from both tumor cells and stromal components, including adipocytes." (PMID 41200178, 2025). "For example, TAMs secrete cytokines such as IL-6 and TNF-α, which upregulate glycolytic enzymes like HK2 and LDHA in tumor cells, amplifying lactate production and fostering a pro-tumorigenic environment." (PMID 41007256, 2025). "Investigating these classical markers in our data, we did observe a statistically significant increase of TNF (TNF‐α) in G1 tumors, FGF14 in G2 tumors, and FGF8, FGF18, and PDGFA in G3 tumor in comparison to pancreatic islet cells." (PMID 39245631, 2025). "Under hypoxic conditions, these exosomes typically contain molecules such as VEGFR2, TNFα, β-catenin, AKT, and EGFR, which send signals that contribute to tumor progression, invasion, metastasis, angiogenesis, and immunosuppression." (PMID 40813991, 2025). "Natural killer cells and CTLs induce tumor cell death by secreting pro-inflammatory cytokines such as interferon-gamma (IFN-γ), tumor necrosis factor-alpha (TNF-α), and cytotoxic mediators such as granzyme and perforin." (PMID 41011224, 2025). "Recent reports have indicated that norank_o__Clostridia_UCG-014 increases SCFA levels, thereby elevating the CD8+ T cell/Treg ratio and promoting TNF-α and IFN-γ secretion in the tumor microenvironment." (PMID 40806124, 2025). "The chemotherapeutic agents substantially increased the proportion and number of CD45+ immune cells, especially the proportion and number of tumor-infiltrating CD8+ TILs, and enhanced the secretion of IFN-γ and TNF-α." (PMID 40236705, 2025). "Pentanoate pre-treated CAR T cells in different tumor models, such as pancreatic cancer, reduced tumor volume and increased IFN-γ and TNF-α production in tumor microenvironment." (PMID 39859572, 2025). "Altogether, high TNF-α expression is prevalent in moderately/poorly differentiated OSCC, and elevated COX-2 expression correlates with larger tumor size and poorer survival in OSCC." (PMID 41259576, 2025). "Among NK cells, CD56+ NK cells typically possess a more effective ability to kill tumor cells and are also more prone to secreting cytokines such as IFN-γ and TNF-α." (PMID 40264767, 2025). "Anti-CD3 antibody-activated polyclonal T cells mediate tumor killing via perforin/FasL pathways;Enhance immunity via IFN-γ/TNF-α secretion." (PMID 40308592, 2025).
tumor (continued). "Upon TNF-α signaling, pharmacologic inhibition of TAK1 sensitized tumor cells to RIPK1-dependent apoptosis." (PMID 41102176, 2025). "ELISA results demonstrated a significant increase in the levels of anti‐tumor cytokines IFN‐γ, TNF‐α, and IL‐2 following treatment with 10e." (PMID 39680480, 2025). "Meanwhile, in vitro investigations have revealed that tumor cells secrete cytokines, including granulocyte colony-stimulating factor (G-CSF), GLUT1, or TNF, which can prolong the lifespan of neutrophils and bolster their viability." (PMID 39925807, 2025). "Tumor necrosis factor alpha (TNF-α) and IFN-γ play important roles in surveillance of tumor growth, therefore TNF-α and IFN-γ production from NK cells co-cultured with Ad5NULL-A20 CD16-BICA transduced cells was measured by ELISA." (PMID 40741595, 2025). "The NF-κB pathway can be activated by cytokines such as TNF-α, IFN-γ and IL-17, as well as oncogenes and tumour suppressors." (PMID 40407951, 2025). "The biomimetic NPs could efficiently accumulate in nsPEF‐pre‐treated PDAC cells, due to the tumor‐targeting features of the neutrophil membrane, which were amplified by the nsPEF‐triggered release of pro‐inflammatory signals (e.g., tumor necrosis factor‐α [TNF‐α])." (PMID 40708975, 2025). "This difference was noted when PBMCs were cocultured with tumor cells in their native state or after stimulation with IFN-γ and TNF-α." (PMID 40459946, 2025). "The cells were treated with TNF-α and TWEAK at the concentration range spanning their tumor-secreted levels detected in VS-CM." (PMID 39923035, 2025). "Subsequent FCM analysis of the tumor-infiltrating CD8+ T cells in the mice revealed increased expression of INFγ, TNF-α, and GzmB across all treatments, with the combined treatment showing the most pronounced effects." (PMID 40365283, 2025). "In vivo, they effectively reduced tumor size in MDA-MB-231 xenograft models, accompanied by increased cytokine levels (IL-2, IL-6, TNF-α, IFN-γ) and many CD3+ cells." (PMID 40281554, 2025). "Mechanistically, we showed that proinflammatory cytokines released by macrophages, in particular TNF-α and IL-1, synergistically upregulate the expression of UPP1 in tumor cells." (PMID 41243973, 2025). "One of the principal explanations for such observations is the fact that α‐SMA is a marker for CAFs which arise from normal fibroblasts via TGF‐β, osteopontin (OPN), interleukin‐1β (IL‐1β), PDGF, TNF‐α, and FGF signals from the tumor." (PMID 39245631, 2025). "Phenotypically, TNFR2+TNF− Tregs expressed higher levels of CD25 in the spleen, and of OX40 and CD71 in both spleen and tumor, compared with TNFR2−TNF+ Tregs." (PMID 40977146, 2025). "In a murine subcutaneous 4T1 tumor model, chitosan-encapsulated HSB facilitated tumor-specific colonization, and thermal induction prompted the production of TNF-α, leading to marked suppression of tumor growth." (PMID 41155984, 2025). "Elevated levels of such common inflammatory factors as TNF-a, CRP, and IL-6 indicate increased tumor activity and higher malignancy, which can exacerbate the patient’s condition." (PMID 40621513, 2025). "Vadimezan (DMXAA/ASA404), the most significant small-molecule flavonoid, triggers Tumor Necrosis Factor α (TNF-α) release, which results in tumor necrosis." (PMID 41155375, 2025). "Pro-inflammatory cytokines, such as tumor necrosis factor alpha (TNF-α) and interleukins, have a role in inflammatory processes and growth of neoplastic diseases." (PMID 39949739, 2025). "Targeting DCA-producing Clostridium scindens by bacteriophages significantly reduces the expression of TNF-α, IFN-γ and granzyme B in intratumoral T cells, subsequently abolishing tumor growth in CRC." (PMID 40770084, 2025). "This was accompanied by reduced infiltration of IFNγ+ and TNF+ CD8+ T cells and proliferating Ki67+ effector T cells within tumours of TAK-242-treated animals without significant effects on other immune cell populations." (PMID 39929976, 2025).